ENSG00000279956 (novel transcript)
Gene: Protein-coding gene on chromosome 2 (48,632,291 to 48,755,724, reverse strand). Ensembl gene ENSG00000279956.
Genetic constraint (gnomAD): Missense variants: 232 observed, 213.58 expected, observed/expected ratio (o/e) 1.09, 90% interval 0.98 to 1.21. Synonymous variants: 105 observed, 91.05 expected, observed/expected ratio (o/e) 1.15, 90% interval 0.98 to 1.36.